POLR2C (RNA polymerase II subunit C)
Description:
Core component of RNA polymerase II (Pol II), a DNA-dependent RNA polymerase which synthesizes mRNA precursors and many functional non-coding RNAs using the four ribonucleoside triphosphates as substrates.
Synonyms: RPB3; RPB31; hRPB33; hsRPB3
Tractability: Small molecule: a structure with a bound ligand is known. PROTAC: ubiquitination databases record sites on it; its protein half-life has been measured.
Gene: Protein-coding gene on chromosome 16 (57,462,660 to 57,472,009, forward strand). Ensembl gene ENSG00000102978.
Subcellular location: Nucleus
Subcellular location (Human Protein Atlas): Nucleoplasm; Cytosol
Pathways (Reactome):
Disease: Abortive elongation of HIV-1 transcript in the absence of Tat; Dengue Virus-Host Interactions; Formation of HIV elongation complex in the absence of HIV Tat; Formation of HIV-1 elongation complex containing HIV-1 Tat; Formation of the HIV-1 Early Elongation Complex; HIV Transcription Initiation; HIV elongation arrest and recovery; Pausing and recovery of HIV elongation; Pausing and recovery of Tat-mediated HIV elongation; RNA Pol II CTD phosphorylation and interaction with CE during HIV infection; RNA Polymerase II HIV Promoter Escape; Signaling by FGFR2 IIIa TM; Tat-mediated HIV elongation arrest and recovery; Tat-mediated elongation of the HIV-1 transcript; Transcription of the HIV genome; Viral Messenger RNA Synthesis
Gene expression (Transcription): Formation of RNA Pol II elongation complex; Formation of the Early Elongation Complex; MicroRNA (miRNA) biogenesis; PIWI-interacting RNA (piRNA) biogenesis; RNA Pol II CTD phosphorylation and interaction with CE; RNA Polymerase II Pre-transcription Events; RNA Polymerase II Promoter Escape; RNA Polymerase II Transcription Elongation; RNA Polymerase II Transcription Initiation; RNA Polymerase II Transcription Initiation And Promoter Clearance; RNA Polymerase II Transcription Pre-Initiation And Promoter Opening; RNA polymerase II transcribes snRNA genes; Transcriptional regulation by small RNAs
Metabolism of RNA: Processing of Capped Intron-Containing Pre-mRNA; mRNA Capping; mRNA Polyadenylation; mRNA Splicing - Major Pathway; mRNA Splicing - Minor Pathway
DNA Repair: Dual incision in TC-NER; Formation of TC-NER Pre-Incision Complex; Gap-filling DNA repair synthesis and ligation in TC-NER; Transcription-Coupled Nucleotide Excision Repair (TC-NER)
Signal Transduction: Estrogen-dependent gene expression
and 3 more pathways
Gene Ontology:
Molecular function: protein binding; DNA-directed RNA polymerase activity; DNA binding; protein dimerization activity
Biological process: transcription by RNA polymerase II; transcription elongation by RNA polymerase II; transcription initiation at RNA polymerase II promoter; DNA-templated transcription
Cellular component: nucleoplasm; nucleus; RNA polymerase II, core complex
Genetic constraint (gnomAD): Loss-of-function variants: 27 observed, 34.19 expected, observed/expected ratio (o/e) 0.79, 90% interval 0.58 to 1.09. The upper end of that interval is the gene's LOEUF score, 1.09, which puts it in group 4 of 6, group 1 being the genes least tolerant of losing a copy. Missense variants: 226 observed, 309.19 expected, observed/expected ratio (o/e) 0.73, 90% interval 0.65 to 0.82. Synonymous variants: 114 observed, 125.99 expected, observed/expected ratio (o/e) 0.9, 90% interval 0.78 to 1.06.
Homologues: Orthologues: chimpanzee POLR2C (100% identical), macaque POLR2C (100% identical), guinea pig POLR2C (99% identical), pig POLR2C (99% identical), rat Polr2c (99% identical), rabbit POLR2C (99% identical), dog POLR2C (95% identical), tropical clawed frog polr2c (95% identical), zebrafish polr2c (90% identical), mouse Polr2c (86% identical), Drosophila melanogaster Polr2C (69% identical), Caenorhabditis elegans rpb-3 (56% identical). Paralogues in human: POLR1C (33% identical), CRIPT (7% identical).
Diseases named in the same sentence as POLR2C in open-access papers:
POLR2C is named in the same sentence as 15 diseases in open-access papers, as found by Europe PMC text mining. Sharing a sentence is not in itself a finding about the gene and the disease. The quoted sentences say what the papers report.
atherosclerosis (1 paper, 2024). A disease characterized by the build-up of fatty material and calcium deposition in the arterial wall resulting in partial or complete occlusion of the arterial lumen. "Among the LAA stroke ecDNA unique genes, there were two hub genes significantly associated with atherosclerosis, including RNA polymerase II subunit C (POLR2C) and Aurora kinase A (AURKA)." (PMID 38506071, 2024).
cancer (4 papers, 2015 to 2024). A tumor composed of atypical neoplastic, often pleomorphic cells that invade other tissues. "Seven genes (BORA, DIS3, POLR2C, FAM175A, EME1, RNF139 and SHMT1) are considered potential biomarkers and/or potential targets for radiotherapy and chemotherapy, as well as cancer susceptibility, cancer progression and metastasis-related genes." (PMID 26517092, 2015). "By contrast, some other genes encoding the polymerase II subunits were characterized by higher methylation in carcinomas than in BOTS (e.g., promoters and/or first exons of POLR2G and POLR2L, as well as the distal promoter of POLR2C, and the cds of POLR2E, GR file)." (PMID 39456618, 2024).
POLR2C also shares sentences with these, for which no sentence is quoted: tumor (2 papers); achromatopsia (1); coronary atherosclerosis (1); Hyperglycemia (1); Insulin resistance (1); Leber congenital amaurosis (1); macular dystrophies (1); myopia (1); osteosarcoma (1); psoriasis (1); retinal degeneration (1); retinal disease (1); virus infection (1).